E2F2 (E2F transcription factor 2)
Diseases named in the same sentence as E2F2 in open-access papers (continued):
Sharing a sentence is not in itself a finding about the gene and the disease.
ovarian carcinoma (37 papers, 2009 to 2025). A malignant neoplasm originating from the surface ovarian epithelium. "E2F2 induced upregulation of MCM4 expression in ovarian cancer, and was significantly associated with the poor prognosis of patients." (PMID 37817427, 2023). "In conclusion, we found that the downregulation of miR-522-3p was strongly associated with the acquisition of paclitaxel resistance in ovarian cancer cells, while its restoration attenuated paclitaxel resistance by targeting E2F2." (PMID 33028939, 2020). "The effects of miR-522-3p and E2F2 in ovarian cancer were examined using public databases, revealing that low miR-522-3p expression and high E2F2 expression were associated with significantly poorer overall survival." (PMID 33028939, 2020). "In this study, we found that the downregulation of miR-522-3p expression was strongly associated with the acquisition of paclitaxel resistance in ovarian cancer cells, while the restoration of miR-522-3p attenuated paclitaxel resistance through the targeting of E2F2." (PMID 33028939, 2020). "furtherly noticed the overexpression of E2F2 in paclitaxel resistance ovarian cancer cells, and inhibiting E2F2 restored paclitaxel sensitivity." (PMID 39999286, 2025). "Examples include BAP1 in cervical and lung cancer, CDK1 in bladder cancer, E2F2 in ovarian cancer, and RHOA, VEGF, NUMB, among others, in oral cancer." (PMID 41373532, 2025). "Similar reports were confirmed in ovarian cancer, where E2F2 was identified as “a transcription factor that promotes proliferative processes”." (PMID 37185737, 2023). "For example, in ovarian cancer, circE2F2 competitively binds to HuR protein, thereby attenuating its contribution to E2F2 mRNA stability, leading to disruption of E2F2 levels and its participating activities such as cell proliferation and migration." (PMID 36072601, 2022). "For instance, LBX2-AS1 promotes E2F2 expression through sponge adsorption of miR-455-5p and miR-491-5p, thereby fostering progression of ovarian cancer." (PMID 34858481, 2021). "In the 655 patients with ovarian cancer in the Kaplan–Meier Plotter database, a higher E2F2 expression level was significantly associated with poorer PFS and OS values (vs. lower E2F2 expression)." (PMID 33028939, 2020). "Previous data suggested that the proliferation-promoting E2F1 and, especially, E2F2 played pivotal roles in the tumor biology of ovarian cancer." (PMID 26967247, 2016). "It was found that interferon-gamma treatment for ovarian cancer caused a reduction of the proliferation-promoting TFs E2F1 and E2F2, at the same time it also increased the inhibiting TFs E2F4 and E2F5." (PMID 20181230, 2010). "Previous studies indicated that E2F2 was a significantly upregulated transcription factor in ovarian cancer epithelial cells and among the OC samples, and simultaneously, high E2F2 expression was negatively associated with tumor stage and outcome among OC patients." (PMID 38807594, 2024). "LBX2-AS1 may promote ovarian cancer progression through miR-455-5p/E2F2, miR-491-5p/E2F2 and miR-4784/KDM5C axis." (PMID 34552959, 2021). "E2F2 overexpression has been reported in cancers, such as ovarian cancer." (PMID 34316028, 2021). "Previous studies revealed that the E2F family of transcription factor 2 (E2F2) plays a crucial role in the development and progression of various cancers, such as ovarian cancer, lung cancer, and hepatocellular carcinoma, promoting cell-cycle progression, stemness, metastasis, and chemoresistance." (PMID 34244473, 2021). "In conclusion, miR-522-3p attenuated the degree of paclitaxel resistance in vitro through the downregulation of E2F2; miR-522-3p supplementation may be a therapeutic target for paclitaxel-resistant ovarian cancer." (PMID 33028939, 2020).
ovarian carcinoma (continued). "Among 381 patients who had received paclitaxel-containing regimens, higher E2F2 expression levels were still significantly associated with poorer PFS and OS values, strongly suggesting that the E2F2 expression in ovarian cancer is related to paclitaxel resistance." (PMID 33028939, 2020). "Similarly, a high E2F2 to E2F4 ratio was reported to be of prognostic value for ovarian cancer-free survival." (PMID 21694727, 2011). "Similarly, studies with histopathology grade 2 ovarian cancers demonstrated that transcription factors E2F-1 and E2F-2 play a critical role in promoting tumor metastasis." (PMID 20196847, 2010). "E2F2 and E2F7 are overexpressed where the first is shown to be an activator and considered as an oncogene, overexpressed in large size and aggressive ovarian cancers." (PMID 19662092, 2009). "In the E2F family of transcription factors, E2F2, E2F3, E2F4, and E2F8 expression is increased and may play oncogenic roles in ovarian carcinoma, and exert the same effects as E2F1." (PMID 28146423, 2017). "Indeed, in ovarian cancer, the proliferation-promoting E2F1 and E2F2 transcription factors were overexpressed, compared with healthy control tissues." (PMID 20226085, 2010). "Further, in order to analyze the correlation between miR-522-3p and E2F2 expression in ovarian cancer cells, the US National Cancer Institute’s NCI60 database—which contains a panel of 60 diverse human cancer cell lines, including seven ovarian cancer lines—was used." (PMID 33028939, 2020).
lung cancer (33 papers, 2010 to 2026). A malignant neoplasm involving the lung. "Similarly, E2F2 (E2F transcription factor 2) is associated with gene regulation not only in lung cancer but also in MI." (PMID 40270498, 2025). "It controls cell proliferation, invasion, and migration in lung cancer, whereas in MI, dysregulation of E2F2 leads to cardiomyopathies." (PMID 40270498, 2025). "Analysis of ONCOMINE, GEPIA, Kaplan-Meier Plotter and cBioPortal databases of E2F2 in patients with Lung cancer shown that the expression level of E2F2 was higher in lung adenocarcinoma and squamous cell lung carcinoma tissues than in lung tissues." (PMID 38807594, 2024). "Functionally, E2F2 was identified as a direct microRNA (miR)-99a target and is involved in miR-99a- suppression of lung cancer stemness and the epithelial-to-mesenchymal transition." (PMID 33924966, 2021). "Further, an in vivo study showed that downregulation of E2F2 inhibits features of stemness and decreases the cancer stem cell population in lung cancer." (PMID 33061852, 2020). "In view of our data, we propose that those lung cancer tumours with high miR-99a levels and corresponding repression of E2F2 and EMR2 would evolve more favourably because of an inhibition of cell proliferation." (PMID 29072692, 2017). "Overall survival in lung cancer patient is known to be poorer in patients with over-expression of E2F1 or E2F2 than in those with normal expression." (PMID 29254182, 2017). "In colon cancer, esophageal neoplasia, and lung cancer, miR-31 acts as an oncogenic miRNA by inhibiting the expression of E2F2, STK40, and PPP2R2A, respectively." (PMID 28783765, 2017). "In non-small cell lung cancer (NSCLC), multiple studies have shown that up-regulation of E2F2 could promote the progression of lung cancer." (PMID 38807594, 2024). "These contradictory findings might in part be due to the different types of tumors in these reports, where E2F2 functioned as a tumor suppressor in Myc-induced cancers and exerted a strong oncogenic effect in lung cancer and glioblastoma cells." (PMID 34056113, 2021). "Moreover, miR-99a expression correlates inversely with E2F2 and directly with β-catenin expression in lung cancer biopsies." (PMID 29072692, 2017). "However, although two studies by bioinformatic analysis revealed that E2F2 mRNA is overexpressed and has prognostic value in The Cancer Genome Atlas (TCGA) and Gene Expression Omnibus (GEO) lung cancer datasets 46, 47, the function of E2F2 in LUAD remains largely elusive." (PMID 35844795, 2022). "E2F1, E2F2, and E2F8 are E2F family members and are overexpressed in lung cancer cells (compared to normal human lung tracheobronchial epithelial cells)." (PMID 36209131, 2022). "MicroRNA miR-99a, which was upregulated in array profiling in patients with SCA, was recently shown as tumor suppressor in lung cancer working together with oncogenic proteins EMR2 and E2F2." (PMID 30332417, 2018). "Metformin down-regulated four E2F family members, E2F1, E2F2, E2F7, and E2F8 in lung cancer cells, with E2F8 being the most prominently down-regulated one." (PMID 29254182, 2017). "The results showed that miRNA may be involved in the regulation of several lung cancer driver genes, such as BCL2, CYCS, E2F2, MCL1, or MYC, among others." (PMID 38791013, 2024). "Intriguingly, it was reported that miR-99a-5p overexpression enhances sensitivity to cisplatin (DDP) and cell apoptosis by suppressing VLDLR expression in lung cancer cells, and miR-99a inhibits two novel oncogenic proteins E2F2 and EMR2 and represses stemness in lung cancer." (PMID 39628814, 2024). "For instance, Li et al24 reported that circPVT1 was up‐regulated in non‐small cell lung cancer (NSCLC) specimens and that it could promote NSCLC cell proliferation and metastasis via sponging miR‐125b and activating E2F2 signalling pathway." (PMID 32166857, 2020).
lung cancer (continued). "E2F transcription factor 2 (E2F2) is one of the activators of the family that controls the transition between the G1 and S phase through various upstream signals, and functions as an oncogene in lung cancer." (PMID 32180804, 2020). "The expression of E2F2 and EMR2 at protein level was studied in 119 lung cancer biopsies." (PMID 29072692, 2017). "In order to test whether E2F2 and EMR2 are involved in lung cancer progression, immunohistochemistry (IHC) analysis from 119 patients was performed." (PMID 29072692, 2017). "Concomitant expression of E2F2 and EMR2 occurred in a subset of lung cancer samples." (PMID 29072692, 2017). "Consequently, the high expression of E2F1 and E2F2, alongside RB1 inactivation and activation of downstream oncogenes, constitutes a complex regulatory network that significantly influences the onset, progression, and prognosis of lung cancer, particularly NSCLC." (PMID 40568194, 2025). "Interestingly, in the present study, we identified that E2F2, E2F3, and E2F4 were not essential genes in lung cancer cells from Project Achilles." (PMID 33924966, 2021).
hepatocellular carcinoma (27 papers, 2015 to 2025). A malignant tumor that arises from hepatocytes. "CCND1, CDK4, MAPK1, CDKN1A, and E2F2 genes are linked to the development of hepatocellular carcinoma." (PMID 33959508, 2021). "In hepatocellular carcinoma, silencing BRD4 or MED1 repressed the transcription of SE-associated genes like SPHK1, E2F2, CCND1, MYCN, and MYC." (PMID 38443991, 2024). "A recent study also revealed that lncRNA AC026401.3 interacts with OCT1 to intensify sorafenib and lenvatinib resistance by activating E2F2 signaling in hepatocellular carcinoma." (PMID 38605354, 2024). "For example, E2F2 is required for hepatocellular carcinoma development, and E2F2 deletion confers protection against hepatocarcinogenesis by preventing lipid storage." (PMID 35075115, 2022). "Increased E2F2 expression is potentially predictive of a poor prognosis in hepatocellular carcinoma and of inflammatory cytokine upregulation." (PMID 35155179, 2021). "The E2F family of transcription factor 2 (E2F2) plays an important role in the development and progression of various tumors, but its association with hepatocellular carcinoma (HCC) remains unknown." (PMID 33115417, 2020). "In hepatocellular carcinoma, E2F2 has been reported to be a tumor-promoter, while in prostate cancer, E2F2 also has been discovered inhibition of tumor cell proliferation through regulation of miRNA let-7a." (PMID 27174918, 2016). "In hepatocellular carcinoma, LINC00847 accelerates cancer progression by acting as a sponge of miR-99a to induce E2F2 expression." (PMID 36864364, 2023). "The study identified a natural-derived small-molecule bufalin that promotes the rapid degradation of E2F transcription factor 2 (E2F2) and inhibits hepatocellular carcinoma." (PMID 36678543, 2022). "For instance, the overexpression of E2F1, E2F2, and E2F3 was observed in patients with hepatocellular cancer, bladder cancer, retinoblastoma, and liposarcoma." (PMID 35392496, 2022). "At present, limited studies on PIK3CD, HRAS, E2F2, BIGF1, WNT4, and VAV3 genes have been reported in hepatoma cells, indicating the need for further research." (PMID 33959508, 2021). "Furthermore, MAPK1, E2F2, CDK4, CDKN1A, CCND1 were found key target genes of hepatocellular carcinoma pathway." (PMID 33959508, 2021).
prostate carcinoma (25 papers, 2010 to 2025). A carcinoma that arises from epithelial cells of the prostate gland. "Direct or indirect targeting of E2F2 has been associated with prostate cancer." (PMID 38605607, 2024). "In prostate cancer, E2F2 activated CIT expression through the Skp2‐p27 axis and conducted androgen deprivation therapy resistance." (PMID 39999286, 2025). "Altogether, these results indicate that E2F1 and E2F2 play a critical role in preserving genome integrity during S-phase in prostate cancer cells." (PMID 36230876, 2022). "Given that prostate cancer is a highly heterogeneous tumor, somatic mutations of clinicopathologically significant E2Fs, including the E2F1, E2F2, E2F3, E2F5, and E2F6, were further investigated in PCa patients." (PMID 35531101, 2022). "One is GSE172094 (siRNA-mediated E2F2 silencing in growth-stimulated LNCaP prostate cancer cells), and the other is GSE155680 (young and senescent HUVECs)." (PMID 36140689, 2022). "E2F1/E2F2 expression correlates with malignancy in prostate cancer (PCa), but its functional significance remains unresolved." (PMID 36230876, 2022). "Our data indicated that overexpression of E2F2 in prostate cancer cells contributed to upregulation of DLEU2, further resulting in aberrant regulation of the miR-582-5p/SGK1 axis." (PMID 35075115, 2022). "E2F1 and E2F2 are upregulated in several cancer types, including prostate cancer (PCa), in which overexpression of these E2Fs correlates with poor clinical outcome." (PMID 36230876, 2022). "Overall, 339 DEGs were identified as overlapping between E2F2-silencing LNCaP prostate cancer cells and the senescent HUVECs." (PMID 36140689, 2022). "Hepatitis B, HTLV-I infection, and prostate cancer are related to transcription factors (Atf4 and E2f2)." (PMID 34987399, 2021). "A previous study reported that E2F2 can promote the development of liver cancer and can also inhibit the proliferation of prostate cancer cell lines." (PMID 29357938, 2018). "Another previous study of prostate cancer has suggested that E2F2 was a predicted direct target of miR-31." (PMID 27174918, 2016). "A recent study demonstrated that let-7a inhibits proliferation of human prostate cancer cells by targeting E2F2 and CCND2." (PMID 22363450, 2012). "E2F2 has been well-characterized as a regulator of the G1-to-S-phase transition, it has been confirmed that it may be novel therapeutic candidate for prostate cancer given its ability to induce cell-cycle arrest and inhibit cell growth." (PMID 38807594, 2024). "We asked whether targeting E2F1 and E2F2 would affect cytotoxicity induced by these antimetabolites in prostate cancer cells." (PMID 36230876, 2022). "Consistent with this notion, depletion of E2F1 and E2F2 by RNA interference in the PC3 prostate cancer cell line significantly raised the percentage of Serine 139-phosphorylated histone H2AX (γH2AX)-positive cells, indicative of an increased DNA damage signaling." (PMID 36230876, 2022). "Here we aimed to define the impact of E2F1/E2F2 deregulation in prostate cancer." (PMID 36230876, 2022). "Moreover, treatment of prostate cancer cells with E2Fi recapitulated the results obtained after siRNA knockdown of E2F1/E2F2 in combination with 5-FU treatment." (PMID 36230876, 2022). "Thus, our results showed that DLEU2 transcription was activated by aberrant E2F2 expression in prostate cancer." (PMID 35075115, 2022). "Mechanistically, DLEU2 promoted serum and glucocorticoid-induced protein kinase 1 (SGK1) expression by acting as an miR-582-5p sponge, and the transcription of DLEU2 was activated by the dysregulation of E2F transcription factor 2 (E2F2) expression in prostate cancer." (PMID 35075115, 2022). "E2F2 is cell-cycle regulator whose expression level increases in the prostate cancer tissue." (PMID 24205155, 2013).
prostate carcinoma (continued). "In this study, we used in vitro and in vivo approaches to investigate whether E2F2 and CCND2 are direct targets of let-7a, and if let-7a acts as a tumor suppressor in prostate cancer by down-regulating E2F2 and CCND2." (PMID 20418948, 2010). "Notably, these findings suggested that E2F2-activated DLEU2 may function as a competing endogenous RNA to facilitate prostate cancer progression by targeting the miR-582-5p/SGK1 axis." (PMID 35075115, 2022). "Finally, we demonstrated that E2F2 contributed to DLEU2 overexpression in prostate cancer." (PMID 35075115, 2022). "The overexpression of E2F2 in prostate cancer cells contributed to upregulation of DLEU2, then facilitated prostate cancer progression, including proliferation, colony formation, migration, and invasion." (PMID 38807594, 2024). "shown that targeting E2F1/E2F2 elicited DNA damage during S phase, leading to premature CDK1 activation and compromised prostate cancer cells viability." (PMID 38807594, 2024). "Similar to E2F2 and E2F4 mentioned previously, E2F6 has been reported in few prostate cancer studies." (PMID 35531101, 2022). "Subsequently, we further investigated the alteration of immune cell components in samples with altered expressions of E2F1, E2F2, E2F3, E2F5, and E2F6 in prostate cancer based on TCGA." (PMID 35531101, 2022). "Cell Senescence caused the differential expression of six genes belonging to the KEGG Pathway Prostate Cancer (PDGFRB, PDGFRA, CCNE2, E2F2, EGFR and ZEB1)." (PMID 35205253, 2022). "We found that E2F target genes involved in nucleotide biosynthesis contribute to maintaining genome stability in prostate cancer cells, but their enzymatic activity is insufficient to prevent replication stress after E2F1/E2F2 depletion." (PMID 36230876, 2022). "Instead, E2F1/E2F2 hinder premature CDK1 activation during S phase, which is key to ensure genome stability and viability of prostate cancer cells." (PMID 36230876, 2022). "Overall, E2F1, E2F2, E2F3, and E2F5 were found to be correlated with the malignant progression of prostate cancer." (PMID 35531101, 2022). "In summary, E2F1, E2F2, E2F3, E2F5, and E2F6 were found to be correlated with the malignant progression of prostate cancer." (PMID 35531101, 2022). "In a prostate cancer cell line, miR-20a directly inhibits the translation of the E2F1, E2F2 and E2F3 mRNA, and the endogenous E2F1, E2F2 and E2F3 bind to the promoter of the miR-17~92 cluster and activate its transcription." (PMID 27282946, 2016). "miR-31 has a known role in prostate cancer and melanoma, suppressing key cell cycle regulators and pro-oncogenic genes such as CDK1, E2F2, EXO1, FOXM1, MCM2, Src or MET." (PMID 25644061, 2015). "Our preliminary experiments indicate that protein levels of both E2F2 and CCND2 are up-regulated in the PC3 prostate cancer cell line." (PMID 20418948, 2010). "We assessed the role of E2F in the sustained upregulation of nucleotide synthesis genes upon 5-FU exposure by transfecting PC3 and DU145 prostate cancer cells with two different sets of siRNA oligos specific for E2F1 and E2F2, and 24 h later treated the cells with 5-FU or vehicle for 72 h." (PMID 36230876, 2022).